PLA2G4A (phospholipase A2 group IVA)
Diseases named in the same sentence as PLA2G4A in open-access papers (continued):
Sharing a sentence is not in itself a finding about the gene and the disease.
nephrosclerosis (1 paper, 2022). Hardening of the kidney due to infiltration by fibrous connective tissue (fibrosis), usually caused by renovascular diseases or chronic hypertension. "Three variants in PLA2G4A also showed associations with the risk of nephrosclerosis, although rs72709847 and rs1569479 were at the border of statistical significance." (PMID 35586043, 2022). "The results from the survival study also pointed to PLA2G4A as a key genetic locus regarding CV risk in nephrosclerosis, with two tag-SNPs (rs932476 and rs6683619) significantly affecting event-free survival." (PMID 35586043, 2022). "A remarkable finding of this study was that several tag-SNPs in PLA2G4A were independent CV risk factors in the nephrosclerosis patients." (PMID 35586043, 2022). "Six tag-SNPs (one in PLA2G7 and five in PLA2G4A) had a significant impact on the risk of accelerated progression in nephrosclerosis patients after adjusting for confounding variables." (PMID 35586043, 2022). "Overall, our results are in line with this background and indicate that the areas of PLA2G4A tagged by the SNPs presented herein hold the potential to be useful biomarkers for CV risk in nephrosclerosis patients." (PMID 35586043, 2022). "The genetic association analysis in the nephrosclerosis cohort revealed a central region of the PLA2G4A gene locus, tagged from rs10578509 to rs17526478 (positions 1:186873127-186882025) that displayed the most significant associations with glomerular filtration and proteinuria values." (PMID 35586043, 2022). "Eight SNPs in PLA2G4A were independent risk factors for CV events in nephrosclerosis patients." (PMID 35586043, 2022). "Our findings also show that variability in the PLA2G4A and PLA2G7 gene loci was associated with several atherosclerotic features in nephrosclerosis patients, including the risk of an accelerated progression." (PMID 35586043, 2022). "We showed that SCARB1 for the risk of nephrosclerosis, PLA2G7 and, especially, PLA2G4A for the CV risk in these patients, are loci that harbor genetic variants whose identification could be of utility in the management of this CKD." (PMID 35586043, 2022). "We screened 1,209 nephrosclerosis patients and controls for 86 tag-SNPs that were identified in the SCARB1, PLA2G4A, and PLA2G7 gene loci." (PMID 35586043, 2022).
neuritis (1 paper, 2023). A neuropathy arising from inflammation of one or more nerves. "The mRNA expressions of PLA2G4A and PTGS2 in neuritis causing multiple cerebral infarctions increased significantly as compared to those in normal subjects." (PMID 37741847, 2023).
renal fibrosis (1 paper, 2022). A final common manifestation of a wide variety of chronic kidney diseases characterized by glomerulosclerosis and tubulointerstitial fibrosis. "The expression levels of both EGR1 and PLA2G4A were detected in renal fibrosis and adjacent normal tissues by qRT-PCR and Western blot method." (PMID 36120336, 2022). "Our results revealed that, compared with normal tissues, the EGR1 and PLA2G4A genes have higher expressions in tissues of renal fibrosis (p < 0.05)." (PMID 36120336, 2022). "The expression levels of both predictive signature genes EGR1 and PLA2G4A were validated in renal fibrosis and adjacent normal tissues by using the qRT-PCR and Western blot methods." (PMID 36120336, 2022). "It was consistent with the PCR results that EGR1 and PLA2G4A have the higher protein expression in the tissues of renal fibrosis as validated by the Western blot analysis." (PMID 36120336, 2022). "We found that SLC4A1, THY1, and GHR were significantly under-expressed in renal fibrosis, and PLA2G4A and EGR1 were significantly over-expressed compared with the normal group." (PMID 36120336, 2022). "Finally, the expression levels of both predictive signature genes EGR1 and PLA2G4A were validated in renal fibrosis and adjacent normal tissues by using qRT-PCR and Western blot method." (PMID 36120336, 2022).
rheumatoid arthritis (1 paper, 2025). A chronic, systemic autoimmune disorder characterized by inflammation in the synovial membranes and articular surfaces. "In rheumatoid arthritis (RA) fibroblastic-like synoviocytes (FLS), MIF upregulates PLA2G4A activity and PLA2G4A mRNA expression." (PMID 40417665, 2025).
Stroke (1 paper, 2024). Sudden impairment of blood flow to a part of the brain due to occlusion or rupture of an artery to the brain. "Thus, the risk of unique genetic variants in PCSK6 and PLA2G4A in South Asian ancestry may indicate a unique endophenotype for stroke, which might also indicate the influence of underlying risk variants for comorbid conditions, for example PLA2G4A in metabolic processes." (PMID 39268810, 2024). "South Asia has two unique variants for stroke, rs528002287 and rs148010464, which maps to genes PCSK6 and the intergenic region of PLA2G4A/LINC01036, respectively." (PMID 39268810, 2024).
Thromboembolism (1 paper, 2024). The formation of a blood clot inside a blood vessel that subsequently travels through the blood stream from the site where it formed to another location in the body, generally leading to vascular occlusion at the distant site. "PLA2G4A also plays a role in the production of pro-thrombotic TXA2 and thus, inhibition of PLA2G4A can reduce platelet aggregation and thromboembolism." (PMID 39268810, 2024).
tuberculosis (1 paper, 2025). A chronic, recurrent infection caused by the bacterium Mycobacterium tuberculosis. "The “MAPK Signaling Pathway” includes genes like MAP3K2, PLA2G4A, and NFKB1, Lastly, the “Tuberculosis” pathway involves IFNGR2, ITGB2, and IL12B." (PMID 40621499, 2025).
vasculitis (1 paper, 2026). "Some experts speculate that autoimmune abnormalities, excessive formation of fibrous tissue, vasculitis, and mutations of PLA2G4A contributory to its pathogenesis." (PMID 41466779, 2026).
tumor (40 papers, 2007 to 2025). "It has also been found that the high expression of PLA2G4A in FLT3-mutated AML is not only an indicator of poor prognosis but also related to drug resistance to tyrosine kinase inhibitors and changes in the tumor microenvironment of AML." (PMID 38033488, 2023). "High ATF6α expression enhances Pla2G4A‐mediated AA metabolism and protects tumor cells against iron downregulation to promote the progression of PCa." (PMID 37746665, 2023). "In terms of eicosanoid synthases, we identified expression of phospholipase Pla2g4a in tumor cells, fibroblasts, and myeloid cells, with minor expression in neutrophils." (PMID 36277993, 2022). "Collectively, RSCRC with abnormal PLA2G4A expression educates γδ T cells into CD39+γδ Tregs to promote tumor progression and metastasis." (PMID 34283812, 2021). "This list includes PLA2G4A, HMGA2, TAGLN and TUSC3, all of which have been implicated in other neoplasias." (PMID 23046790, 2012). "Similarly, Pla2g4a upregulation promoted tumor progression and induced the expression of CD39 on γδ-TILs." (PMID 34283812, 2021). "In addition, the results of H&E staining showed that the tumor invaded into the deep muscle layer; on the other hand, it breaks through the serosal layer to achieve distal metastasis, indicating that upregulation of Pla2g4a promotes tumor invasion." (PMID 34283812, 2021). "Pla2g4a upregulation resulted in a substantial elevation of tumor weight and metastasis." (PMID 34283812, 2021). "We hypothesize that PLA2G4A may also play an important role in the formation of tumor-related inflammation." (PMID 34131250, 2021). "Since numerous reports on dysregulation of PLA2G4A in a variety of cancers point to a possible role of this gene in tumor growth, tumor cell migration and tumor angiogenesis, we focused on the HERV-Ec1 provirus and its potential role in regulation of the PLA2G4A gene." (PMID 23145155, 2012). "Tumor tissues showed obviously higher expression levels of PLCG2, PLA2G4A, and HTR2C than the normal esophageal tissues." (PMID 35309940, 2022). "When the level of PLA2G4A increases, CD39+γδ Tregs would be induced to form an immunosuppressive microenvironment and promote tumor progression (the present study provided relevant evidence)." (PMID 34283812, 2021). "While down-regulation of genes such as CYP4A11, PLA2G4A, PLA2G3, LTC4S, CYP27A1, HMGCS2 and PDPK1 reduced patient overall survival time in most tumor types." (PMID 31074374, 2019). "Furthermore, the PLA2G4A/AA axis drives CD39+γδ T-regulatory cells (Tregs) polarization, exacerbating tumor progression and metastasis." (PMID 41210682, 2025). "Among them CCNB1, MIF, PLA2G4A may be regarded as oncogenes, whereas RNASE3, APOE, FOXO1, KIT, and EGR1 may be tumor suppressor genes." (PMID 37065484, 2023). "In this tumor, we also observed not only upregulation of FGF ligands (FGF19 and FGF20; 88- and 68-fold, respectively) but also a very strong upregulation of the phospholipase PLA2G4A (345-fold)." (PMID 34271981, 2021). "Therefore, we further studied and confirmed that overexpression of PLA2G4A induced the activation of the CD39/adenosine pathway in γδ T cell to impair its antitumor response, consequently promoting tumor progression." (PMID 34283812, 2021). "Phospholipases, such as PLA2G16, PLA2G12A and PLA2G4A were not highly expressed in the tumour tissues." (PMID 28886030, 2017). "Within the tumor population, we identified expression of phospholipase enzymes PLA2G2A and PLA2G4A and PTGS2 (COX2), but not PTGS1 (COX1)." (PMID 36277993, 2022).
cancer (38 papers, 2012 to 2026). A tumor composed of atypical neoplastic, often pleomorphic cells that invade other tissues. "Scd, Scd2, Dgat2, Fads2, Lpin1, Gpat3, Acaa2, Lpcat3, Pcyt2 and Pla2g4a have been reported to be closely associated with cancer." (PMID 35122680, 2022). "Analysis of 24,375 patient samples from cancers of 12 different tissue origins showed the highest expression of the gene encoding cPLA2α (PLA2G4A) in cancers originating from the respiratory system and skin." (PMID 34946532, 2021). "Previous study found that the common PLA2G4A upregulation in cancer cells contributes to their migration and invasion and is significantly correlated with unfavorable prognosis." (PMID 35957912, 2022). "The choline metabolism in cancer pathway (ecb05231) leads to increased levels of choline-containing precursors via the modulation of enzymes (e.g., PLA2G4A, PLD1)." (PMID 36553455, 2022). "Our exploration of public data demonstrated higher expression of PLA2G4A in human cancers of specific tissue origins, including the respiratory system, skin, digestive organs, and urinary organs." (PMID 34946532, 2021). "This is in line with the already described oncogenic properties of PLA2G4A in various cancers, and supports the functional and prognostic value of PLA2G4A in AML that warrants further investigations." (PMID 34502319, 2021). "For patient ID 110, this notably included MAP2K2, KIT, VEGFA, A2M, ICAM1 and PLA2G4A, all of which are involved in cancer development." (PMID 34771574, 2021). "These lines were selected based on their differential expression of HOXA9, MEIS1, and PLA2G4A in the Cancer Cell Line Repository sequencing data." (PMID 34502319, 2021). "Based on the finding that hematological cancer cell lines were more sensitive to cPLA2α inhibition than solid cancer cell lines, we next explored PLA2G4A gene expression in different cancers of blood origin." (PMID 34946532, 2021). "To compare the gene expression of PLA2G4A between cancer patients and healthy individuals, we used the cancer microarray database “Oncomine”, which contains 65 gene expression datasets from over 4700 microarray experiments." (PMID 34946532, 2021). "In the case of ovarian cells, PLA2G4A as well as PLA2G4C were lower in cancer cell lines compared to normal." (PMID 23626839, 2013). "For example, the overexpression of the PLA2G4A gene has been identified in several cancer types." (PMID 35241089, 2022). "To elucidate whether overexpression of PLA2G4A in cancer cells activates the adenosine pathway of γδ T cells, we overexpressed Pla2g4a in the CT26 cell line." (PMID 34283812, 2021). "PLA2G4A is considered an important target for prevention and treatment of cancers." (PMID 33302383, 2020). "We also found higher gene expression of PLA2G4A in both MM and MGUS patients than in healthy individuals, supporting MM as an interesting cancer for further investigation." (PMID 34946532, 2021). "Another very prominent pathway in cancer is ERK/MAPK signaling (p = 3.47 × 10−2; ESR1, FYN, ITGA3, PIK3R3, PLA2G4A, PLA2G5, RPS6KA5), which is the core of the signaling network involved in regulating cell growth, development, and division and a target of many cancer therapeutics." (PMID 35106465, 2022). "While in NOR, PLA2G4A (phospholipase A2, group IVA cytosolic, calcium-dependent) was not expressed (AVE(NOR) = 0), in all three cancer regions it was turned on (AVE(PTA) = 0.55, AVE(PTB) = 0.72, AVE(CWM) = 0.54)." (PMID 33302383, 2020).
infection (12 papers, 2013 to 2025). The state of being infected such as from the introduction of a foreign agent such as serum, vaccine, antigenic substance or organism. "Numerous research studies have provided evidence that infection caused by Staphylococcus aureus enhances the activity of PLA2G4A." (PMID 38371936, 2024). "Several genes were significantly upregulated (Pla2g4a, Pla2g4c, Pla2g7, Ptgs1, Ptgs2, Pla1, Tbxas1) or downregulated (Alox5, Pla2g2d, Pla2g1b, Pla2g4b, Pla2g4f) during infection." (PMID 35812400, 2022). "While Pla2g4a showed a moderate induction of log2FC = 2.9, expression of Ptgs2 was induced dramatically with log2FC = 11.5 at 4 h post infection, hinting at its importance during infection." (PMID 30669987, 2019). "The transcriptome results obtained in the current study show that both acetylhydrolase (PAFAH/Pla2g7), which regulates PAF metabolism, and cytosolic phospholipase A2 (Pla2g4a), which is involved in the remodeling pathway, were significantly upregulated after infection." (PMID 40463366, 2025). "Interestingly, in a recent study Pla2G4a among others was found as a signature of infected mouse liver after infection with L. donovani." (PMID 37187743, 2023). "Despite being important for infection, cleavage of FASN and PLA2G4A hints that lipid synthesis and membrane remodeling are regulated during infection, possibly to facilitate specific steps of the viral life cycle." (PMID 38953667, 2024). "Most candidate proteins such as PLA2G4A, FASN, HNRNPH2, and LARP4 showed detectable cleavage products at 5 h.p.i. that were stable at later times of infection." (PMID 38953667, 2024). "To examine their roles in infection, we monitored the viral yield of CVB3-infected cells treated with inhibitors that block FASN and PLA2G4A enzymatic activities." (PMID 38953667, 2024). "When looking at the overall trend in protein expression over the whole time-course, PLA2G4A and PLA2G2A appear to share the same expression profile with a clear increase at 24 h post-infection." (PMID 32575076, 2020). "In addition, genes related to PI3K-Akt signaling pathway showed downregulation and inhibition at 48 h post-infection, such as GP1BA, PIK3CA, AKT3, and PLA2G4A." (PMID 37211158, 2023).
mental illness (2 papers, 2022 to 2024). "One previous study confirmed that another three family members, PLA2G4A, PLA2G4B, and PLA2G4C, are strongly associated with mental illness in the Chinese population." (PMID 36056316, 2022).
neurological disease (2 papers, 2022). "In LHQW, arctiin, corymbosin, and aloe-emodin target neurological disease-related genes (GRM1 and GRM5), whereas in QFPD, isofucosterol, baicalein, nobiletin, oroxylin A, epiberberine, and piperlonguminine target immunity- and inflammation-related genes (mTOR and PLA2G4A)." (PMID 36210820, 2022).
myopathies (1 paper, 2015). "PLA2G4A has previously been implicated in broad spectrum skeletal muscle myopathies in broiler chickens." (PMID 25994290, 2015).
PLA2G4A also shares sentences with these, for which no sentence is quoted: Cognitive impairment (3 papers); colon cancer (3); angioedema (2); cervical cancer (2); depression (2); Hyperglycemia (2); Hypertension (2); myocardial infarction (2); neurodegenerative disease (2); Sepsis (2); adenocarcinoma (1); Atrophy (1); B-cell lymphocytic leukemia (1); behavioral disorders (1); breast invasive carcinoma (1); bronchiectasis (1); cardiovascular diseases (1); cat-eye syndrome (1); celiac disease (1); Cerebral ischemia (1); cholangiocarcinoma (1); chronic myeloid leukemia (1); colorectal tumors (1); dementia (1); eosinophilia (1); epilepsy (1); esophageal adenocarcinoma (1); experimental autoimmune encephalomyelitis (1); Familial adenomatous polyposis (1); female infertility (1).
A further 29 diseases each share a sentence with PLA2G4A in 1 paper.